BMP1 (bone morphogenetic protein 1)
Diseases named in the same sentence as BMP1 in open-access papers (continued):
Sharing a sentence is not in itself a finding about the gene and the disease.
Obesity (4 papers, 2018 to 2024). Accumulation of substantial excess body fat. "Our study indicates that detecting an important link between BMP1 in obese patients will help elucidate the pathogenesis of obesity and come up with a potential therapeutic candidate." (PMID 39280566, 2024). "Unlike many studies in the literature about the correlation between BMP1, HDL-C, and LDL-C, our study proves to be significant, being the first to demonstrate the correlation between BMP1 and obesity." (PMID 39280566, 2024). "Our study aims to compare the serum levels of bone morphogenetic protein 1 (BMP1), neuregulin 4 (NRG4), and apolipoprotein A5 (ApoA5) in obese and non-obese individuals and investigate their association with obesity." (PMID 39280566, 2024). "Althoughit is generally known from recent studies that BMP1 plays a role in osteogenesis, some encouraging results were obtained in our study indicating that BMP1 may play a role in the pathogenesis of obesity." (PMID 39280566, 2024). "Our study aimed to research the correlation between obesity and serum BMP1, NRG4, and ApoA5 levels." (PMID 39280566, 2024). "BMP1 levels were also an independent significant predictor of obesity together with AST/ALT ratio and QUICKI in this study, suggesting that it may exhibit a metabolic deterioration in obese individuals." (PMID 39280566, 2024). "Although BMP1 has been shown to play a role in osteogenesis in studies conducted to date, we obtained encouraging results suggesting that BMP1 might play a role in the pathogenesis of obesity." (PMID 39280566, 2024). "BMP1, QUICKI values, and AST/ALT ratios proved to be statistically significant in obesity through the univariable logistic regression analysis (β = 1.066, p = 0.048; β = 0.0001, p = 0.001, and β = 3.707, p = 0.003, respectively)." (PMID 39280566, 2024). "Our study aims to compare the relationship between the demographic characteristics and the biochemical parameters of the participants and biomarkers (BMP1, NRG4 and ApoA5) thought to be related to obesity." (PMID 39280566, 2024). "In this study, we found that the independent variables, i.e., BMP1, QUICKI values, and AST/ALT ratio, were significantly related to obesity." (PMID 39280566, 2024). "Our proteomics pathway analyses highlighted other proteins involved in lipoprotein metabolism (APOA1, BMP1, FABP3 and ANGPTL4) and that are key markers in obesity and NAFLD56–58." (PMID 32514005, 2020). "Our study showed that BMP1 levels in obese patients were higher than in non-obese patients, and BMP1 levels are an independent significant predictor of obesity on univariate analysis." (PMID 39280566, 2024). "In addition, proteomic pathway analyses highlighted other proteins involved in lipoprotein metabolism (APOA1, BMP1, FABP3 and ANGPTL4) that are key markers in obesity and NAFLD." (PMID 36678141, 2023). "As our patient population was small, we think that the BMP1 level may not have predicted obesity." (PMID 39280566, 2024).
chronic kidney disease (3 papers, 2016 to 2022). Impairment of the renal function secondary to chronic kidney damage persisting for three or more months. "Besides, BMP1 is necessary to generate functional high-density lipoprotein particles for reverse cholesterol transport, and contributes to renal fibrosis in chronic kidney disease by affecting the maturation and deposition of collagen and subsequent profibrotic responses and inflammation." (PMID 32953253, 2020). "ATP2B4 and BMP-1 antibodies increase in atherosclerosis-related diseases, such as CI, CAD, DM and chronic kidney disease." (PMID 28936256, 2016). "We have recently reported novel atherosclerosis-related antibody markers, such as antibodies against RPA2 for stroke, antibodies against SOSTDC1 and TUBB2C for CI and DM, and antibodies against ATP2B4 and BMP-1 for atherosclerosis-related diseases, such as CI, CAD, DM and chronic kidney disease." (PMID 28936256, 2016).
colorectal cancer (3 papers, 2018 to 2019). A primary or metastatic malignant neoplasm that affects the colon or rectum. "CSMD2 encoding a member of the C1r/C1s, Uegf, Bmp1 (CUB) and sushi multiple domain protein (CSMD) family – is a candidate TSG associated with colorectal cancer." (PMID 31200735, 2019). "What is noteworthy is that, NCBI GEO gene expression database of TECs in colorectal cancer and lymphoma also verified the specific high expression of 7 out of these 12 ECM associated genes in TECs from colorectal cancer and lymphoma, i.e. SPON2, BMP-1, FN1, POSTN, THBS2, VCAN and AEBP1." (PMID 29541388, 2018).
liver fibrosis (3 papers, 2022 to 2024). "Blocking BMP1 by small molecule or antibody inhibitors has been linked to anti-fibrotic activity in the preclinical models of skin, kidney and liver fibrosis." (PMID 35361882, 2022). "Bmp-1 assumes a crucial function in this process by activating EGFR signalling in hepatocytes.Additionally, in fibrotic mice with a deficiency in Periostin, the reduction in liver fibrosis was counteracted by the introduction of exogenous Bmp-1, which coincided with the progression of EMT." (PMID 38216590, 2024). "The findings provide evidence of the essential role of Bmp-1 in Periostin-provoked liver fibrosis through hepatocyte EMT." (PMID 38216590, 2024). "It plays a crucial role in mediating the pro-fibrotic communication between HSCs and hepatocytes through the involvement of Bmp-1, thereby influencing the development of liver fibrosis." (PMID 38216590, 2024). "In line with the exacerbated liver fibrosis and elevated Bmp-1 levels, the expression of hepatocyte EMT markers, including N-cad, Vim, and EGFR was increased, while E-cad expression decreased in the livers of Periostin-deficient mice." (PMID 38216590, 2024). "BMP1 exhibits expression as several spliced isoforms, with antibodies targeting the BMP1-3 isoform proving effective in impairing CCl4-induced rat liver fibrosis." (PMID 38928229, 2024). "Mechanistically, bone morphogenetic protein-1 (Bmp-1) is essential involved in the pro-fibrotic communication between Periostin-expressing aHSCs and hepatocytes, consequently promoting the progression of liver fibrosis." (PMID 38216590, 2024). "Bmp-1 and Periostin should be potential therapeutic targets for liver fibrosis." (PMID 38216590, 2024). "Thus, it is plausible that BMP1 may play a much more important role in skin, kidney and liver fibrosis than in lung fibrosis." (PMID 35361882, 2022). "Periostin-overexpressing HSCs, exhibiting a proliferative aHSC phenotype, release bone morphogenetic protein-1 (Bmp-1), which activates EGFR signaling, inducing hepatocyte EMT and contributing to liver fibrosis." (PMID 38216590, 2024).
melanoma (3 papers, 2017 to 2022). A malignant, usually aggressive tumor composed of atypical, neoplastic melanocytes. "Finally, C1q co-localized with BMP-1 in skin biopsies following melanoma excision and from patients with recessive dystrophic epidermolysis bullosa." (PMID 29209066, 2017). "The results indicated that a high expression of BMP1 contributes to poor immunotherapy response in melanoma and urothelial cancer, which had never been reported in previous papers." (PMID 36267461, 2022). "In this regard, the immunofluorescence data showed clear evidence of co-localization of C1q and BMP-1 in biopsies from clinically non-inflamed skin, adjacent to melanoma excision sites and from patients suffering from RDEB." (PMID 29209066, 2017). "C1q protein was expressed in biopsies from clinically non-inflamed skin from sites adjacent to melanoma excision and also from RDEB patient skin, as well as BMP-1." (PMID 29209066, 2017).
renal fibrosis (3 papers, 2020 to 2022). A final common manifestation of a wide variety of chronic kidney diseases characterized by glomerulosclerosis and tubulointerstitial fibrosis. "Additionally, Bmp1-3 can accelerate renal fibrosis in the mouse model of CKD by increasing the deposition of ECM attenuated by polyclonal antibodies specifically against Bmp1 or Bmp3." (PMID 36523757, 2022). "In summary, Bmp1 may serve as a target for renal fibrosis therapy." (PMID 36523757, 2022). "Among the LLC1-derived nephrotoxic secretory proteins, ANGPL2, BMP-1, DCN, FN1, and MCP-1 have been shown to contribute to TGF-β signaling-dependent renal fibrosis." (PMID 33260558, 2020).
astrocytomas (2 papers, 2015 to 2020). "In contrast, stepwise upregulation of HIF1A observed in our cases of diffusely infiltrative astrocytomas associated with high expression of LOX and BMP1 suggest progressive activation of both angiogenic and invasive pathways." (PMID 25790191, 2015). "The results demonstrate that increased expression and activity of LOX, BMP1 and HIF1A were positively correlated with the malignant grade of astrocytomas." (PMID 25790191, 2015). "In the present study, we investigated the expression of LOX, BMP1 and HIF1A in astrocytomas of different malignant grades." (PMID 25790191, 2015). "BMP1 and HIF1A were positively correlated with the malignant grade of astrocytomas, but no research reported their direct or indirect relationship." (PMID 31155610, 2020). "The purpose of our study was to characterize LOX, BMP1 and HIF1A expression by real-time PCR in astrocytomas with WHO grades I to IV compared to non-neoplastic brain tissue." (PMID 25790191, 2015). "LOX, BMP1 and HIF1A expression analysis by qRT-PCR showed great variability in astrocytomas of all malignant grades when compared to non-neoplastic samples." (PMID 25790191, 2015).
colon cancer (2 papers, 2020 to 2022). "BMP1 is involved in the TFG-β and BMP signalling pathways, and it has been reported that BMP1 expression upregulation is involved in gastric, lung, and colon cancer progression." (PMID 35936012, 2022).
glaucoma (2 papers, 2020 to 2021). Increased pressure in the eyeball due to obstruction of the outflow of aqueous humor. "Therefore, it is difficult to predict whether BMP1 has beneficial or deleterious effects in glaucoma." (PMID 32953253, 2020). "We identified several key genes, including BMP1, DMD and GEM, that may be involved in the pathogenesis of glaucoma." (PMID 32953253, 2020). "We also identified three key genes, BMP1, DMD and GEM that might be served as potential biomarkers of glaucoma." (PMID 32953253, 2020). "Our results indicate that BMP1, DMD and GEM are potential biomarkers of glaucoma." (PMID 32953253, 2020).
lung fibrosis (2 papers, 2022 to 2024). "This unique mouse model allows us to fully employ a genetic approach to determine the contribution of BMP1 to lung fibrosis in animals." (PMID 35361882, 2022). "Next, we investigated whether inducible deletion of Bmp1 protects mice from the development of lung fibrosis in the bleomycin model." (PMID 35361882, 2022). "To complement our observation in human samples, we sought to determine whether BMP1 expression is increased in the mouse model of lung fibrosis." (PMID 35361882, 2022). "Considering the important role of BMP1 in procollagen processing, maturation and deposition, we hypothesized that BMP1 may be a critical determinant of lung fibrosis and could be a potential therapeutic target for progressive fibrotic diseases such as IPF." (PMID 35361882, 2022). "Therefore, we reason that BMP1 may be important for the pathogenesis of lung fibrosis and BMP1 could be a potential therapeutic target for progressive fibrotic disease such as idiopathic pulmonary fibrosis (IPF)." (PMID 35361882, 2022). "However, when these Bmp1 conditional knockout (cKO) mice were tested in the bleomycin model of lung fibrosis, we observed that BMP1 deficiency does not prevent lung fibrosis in mice." (PMID 35361882, 2022). "There is a dramatic increase in gene expression of BMP1 in fibroblasts and myofibroblasts in IPF lungs compared to control subjects, but BMP1 has been shown to not be required for development of lung fibrosis in a murine model of PF." (PMID 39142248, 2024). "Further examination of CICP production also revealed that BMP1 is not necessary for type I procollagen C-term processing and maturation during lung fibrosis." (PMID 35361882, 2022). "Collectively, these results suggest that BMP1 does not contribute to the pathogenesis of lung fibrosis in the bleomycin model." (PMID 35361882, 2022). "Taken together, we provided the first genetic evidence that BMP1 is not required for the development of lung fibrosis in mice, thus arguing against the drug target candidacy of BMP1 for IPF." (PMID 35361882, 2022). "To our surprise, we found that BMP1 is clearly not required for lung fibrosis in the bleomycin model and BMP1 does not contribute to type I procollagen C-term processing." (PMID 35361882, 2022). "Overall, our study provided the first genetic evidence that BMP1 is not required for lung fibrosis and BMP1 is not the major proteinase to cleave C-term of type I procollagen in the bleomycin model." (PMID 35361882, 2022). "Based on these results, we propose that BMP1 is not required for lung fibrosis in mice and BMP1 may not be considered a candidate therapeutic target for IPF." (PMID 35361882, 2022). "The lack of anti-fibrotic effects in Bmp1 cKO mice prompted us to explore whether BMP1 modulates procollagen, particularly type I procollagen, C-term processing during the development of lung fibrosis in the bleomycin model." (PMID 35361882, 2022). "We found that Bmp1 deletion does not protect mice from lung fibrosis triggered by bleomycin." (PMID 35361882, 2022).
myocardial infarction (2 papers, 2019 to 2022). Gross necrosis of the myocardium, as a result of interruption of the blood supply to the area, as in coronary thrombosis. "Secreted frizzled-related protein 2 (Sfrp2) was recently reported to play a critical role on cardiac fibrosis after myocardial infarction (MI), partially through activating bone morphogenic protein 1 (BMP1) to initiate a feed-forward loop between TGF-β and BMP1 7-9." (PMID 31695768, 2019). "Starting from the evidence that a specific isoform of the Bone Morphogenetic Protein 1 (BMP1.3) is particularly elevated in both patients and animal models of myocardial infarction, here we assess whether its inhibition by a specific monoclonal antibody reduces cardiac fibrosis." (PMID 35013172, 2022).
osteoporosis (2 papers, 2025 to 2026). A condition of reduced bone mass, with decreased cortical thickness and a decrease in the number and size of the trabeculae of cancellous bone (but normal chemical composition), resulting in increased fracture incidence. "Additionally, BMP‐1 dysregulation has been implicated in osteoporosis and OA." (PMID 41502501, 2026). "In an ovariectomized mouse model of osteoporosis, treatment with E2 significantly upregulated the expression of BMP1 in the metaphyseal tissues." (PMID 41247840, 2025).
pancreatic cancer (2 papers, 2021 to 2023). "We surveyed the coexpressed genes in the pancreatic cancer TCGA dataset and found that BMP1 was coexpressed with a large number of matrisome genes and especially collagen-related genes, such as COL1A1 and COL1A2." (PMID 33879793, 2021). "As bone morphogenic protein 1 (BMP1) promotes collagen deposition, the study first confirmed that BxPC3 (human pancreatic cancer cells) overexpressing BMP1 (lenti-BMP1) could enhance collagen subunit α1(I) protein levels in vitro." (PMID 37627163, 2023).
rectal cancer (2 papers, 2014 to 2022). A primary or metastatic malignant neoplasm that affects the rectum. "The underlying correlation between TGFB1 and BMP1 in rectal cancer must be analyzed and identified ulteriorly." (PMID 36267461, 2022). "RUNX3 was significantly associated with rectal cancer survival, while BMP1 (PARTP = 0.099) and BMPR1A (PARTP = 0.085) were marginally significant." (PMID 25541970, 2014).
Stroke (2 papers, 2018). Sudden impairment of blood flow to a part of the brain due to occlusion or rupture of an artery to the brain. "We have screened autoantibody levels in the sera of patients with ischemic stroke and report TUBB2C, ATP2B4, BMP-1, DHPS, and SH3BP5 as possible antigens that may be implicated in the development of stroke." (PMID 29507658, 2018).
thyroid cancer (2 papers, 2023). "This analysis revealed that seven of the novel identified variants were located in genes previously associated with thyroid cancer: MSH6, FOXM1, EPCAM, HOOK3, BMP1, TG and NTRK1." (PMID 37175550, 2023). "BMP-1 expression has been observed in thyroid cancer-related ossification." (PMID 38132395, 2023). "The Enigma may also have an interaction with BMP-1 as BMP-1 is highly expressed in thyroid cancer ossification." (PMID 38132395, 2023). "Our hypothesis was that the Enigma could interact with BMP-1 in the context of malignant calcification in thyroid cancer." (PMID 38132395, 2023). "Our findings suggest expression of the Enigma and BMP-1 may promote different pathways within thyroid cancer tissue." (PMID 38132395, 2023). "We observed a strong colocalization signal of the Enigma and BMP-1 and hypothesized that the Enigma may recruit BMP-1 in malignant calcification in thyroid cancer." (PMID 38132395, 2023). "The Enigma has been colocalized with bone morphogenetic protein 1 (BMP-1), which is known to promote calcification and carcinogenesis in thyroid cancer." (PMID 38132395, 2023).
Arthritis (1 paper, 2015). Inflammation of a joint. "Moreover, BMP1 has been linked to arthritis and bone formation and may increase bone formation in several ways." (PMID 25889670, 2015).
Autoimmunity (1 paper, 2022). The occurrence of an immune reaction against the organism's own cells or tissues. "Both NK activation and autoimmunity are linked to BMP signaling, e.g., via an autocrine activation pathway via BMP receptors and BMP ligands in NK cells, which fits our identified target genes BMP1, BMP2, BMP3, BMP7, BMP6, BMPER, BMPR1B, and, most importantly, BMPR2." (PMID 35455956, 2022).
breast tumors (1 paper, 2019). "We found that signal peptide-CUB (complement protein C1r/C1s, Uegf, and Bmp1)-EGF (epidermal growth factor) domain-containing protein 2 (SCUBE2), a tumor suppressor gene, was hypermethylated in breast tumors." (PMID 31404982, 2019).
Camurati-Engelmann disease (1 paper, 2021). Camurati-Englemann disease (CED) is a rare, clinically variable bone dysplasia syndrome characterized by hyperostosis of the long bones, skull, spine and pelvis, associated with severe pain in the extremities, a wide-based waddling gait, joint contractures, muscle weakness and easy fatigability. "A total of 7/47 probands suspected with OI carried variants in 6 disease-causing genes, namely, 1 IFITM5, 1 CRTAP, 2 BMP1, 1 PLS3, and 1 COL1A2 (c.432 + 4_432 + 7delAGTA was ignored previously), and 1 case of Camurati-Engelmann disease with pathogenic variants in TGFβ-1, which was misdiagnosed." (PMID 34557487, 2021).
colitis (1 paper, 2020). Inflammation of the colon. "Stainings for Adamts1, Adamts5, and Bmp1 showed similar distribution patterns as the MPO-staining, indicating that these proteases are contributed not by the colon epithelium, but by invading neutrophils/monocytes on colitis induction." (PMID 32160911, 2020).